SAV1 (salvador family WW domain containing protein 1)
Description:
Regulator of STK3/MST2 and STK4/MST1 in the Hippo signaling pathway which plays a pivotal role in organ size control and tumor suppression by restricting proliferation and promoting apoptosis. The core of this pathway is composed of a kinase cascade wherein STK3/MST2 and STK4/MST1, in complex with its regulatory protein SAV1, phosphorylates and activates LATS1/2 in complex with its regulatory protein MOB1, which in turn phosphorylates and inactivates YAP1 oncoprotein and WWTR1/TAZ. Phosphorylation of YAP1 by LATS1/2 inhibits its translocation into the nucleus to regulate cellular genes important for cell proliferation, cell death, and cell migration. SAV1 is required for STK3/MST2 and STK4/MST1 activation and promotes cell-cycle exit and terminal differentiation in developing epithelial tissues. Plays a role in centrosome disjunction by regulating the localization of NEK2 to centrosomes, and its ability to phosphorylate CROCC and CEP250. In conjunction with STK3/MST2, activates the transcriptional activity of ESR1 through the modulation of its phosphorylation.
Synonyms: WW45; WWP4; salvador; SAV
Tractability: Small molecule: a structure with a bound ligand is known. PROTAC: ubiquitination databases record sites on it.
Gene: Protein-coding gene on chromosome 14 (50,632,058 to 50,668,337, reverse strand). Ensembl gene ENSG00000151748.
Subcellular location: Nucleus; Cytoplasm
Subcellular location (Human Protein Atlas): Cytosol
Pathways (Reactome):
Signal Transduction: Signaling by Hippo
Gene Ontology:
Molecular function: identical protein binding; protein binding; protein serine/threonine kinase activator activity; transcription regulator activator activity; molecular adaptor activity
Biological process: hippo signaling; protein stabilization; negative regulation of cell population proliferation; positive regulation of apoptotic process; apoptotic process; regulation of cell population proliferation; regulation of gene expression; signal transduction
Cellular component: cytoplasm; cytosol; nucleus
Genetic constraint (gnomAD): Loss-of-function variants: 23 observed, 46.06 expected, observed/expected ratio (o/e) 0.5, 90% interval 0.36 to 0.71. The upper end of that interval is the gene's LOEUF score, 0.71, which puts it in group 2 of 6, group 1 being the genes least tolerant of losing a copy. Missense variants: 446 observed, 467.08 expected, observed/expected ratio (o/e) 0.95, 90% interval 0.88 to 1.03. Synonymous variants: 155 observed, 165.69 expected, observed/expected ratio (o/e) 0.94, 90% interval 0.82 to 1.07.
Homologues: Orthologues: chimpanzee SAV1 (100% identical), macaque SAV1 (99% identical), dog SAV1 (98% identical), pig SAV1 (97% identical), guinea pig SAV1 (96% identical), rat Sav1 (95% identical), mouse Sav1 (94% identical), rabbit SAV1 (83% identical), tropical clawed frog sav1 (81% identical), zebrafish sav1 (68% identical), Drosophila melanogaster sav (37% identical), Caenorhabditis elegans sav-1 (27% identical). Paralogues in human: MAGI3 (29% identical), MAGI1 (27% identical), MAGI2 (27% identical), GRIP1 (15% identical), GRIP2 (14% identical), MAGIX (6% identical).
Diseases named in the same sentence as SAV1 in open-access papers:
SAV1 is named in the same sentence as 71 diseases in open-access papers, as found by Europe PMC text mining. Sharing a sentence is not in itself a finding about the gene and the disease. The quoted sentences say what the papers report.
hepatocellular carcinoma (13 papers, 2011 to 2024). A malignant tumor that arises from hepatocytes. "SAV1 expression has been linked to progression in gastric cancer, hepatic carcinoma and pancreatic cancer." (PMID 38999991, 2024). "Authors found Sav1 loss to accelerate hepatocellular carcinoma in the context of Pten-deficient steatotic liver in vivo." (PMID 31338332, 2019). "It has been observed that mice with liver-specific ablation of SAV1 manifest an increased liver size and expansion of hepatic progenitor cells and, eventually, develop hepatomas." (PMID 38136317, 2023). "The liver-specific SAV1 knockout mice developed tumors, thought to originate from the transformed oval cells, with a mixed (hepatocellular carcinoma/cholangiocarcinoma) phenotype, distinct from hepatocellular carcinoma, originating from the aberrant proliferation of hepatocytes." (PMID 38136317, 2023). "In fact, transgenic overexpression of YAP and liver-specific knockout of Mst1/2 or Sav1 induce abnormal liver expansion in terms of size, and eventually hepatocellular carcinoma formation (HCC)." (PMID 22830020, 2012). "For example, two groups have recently reported that conditional knockout mice, in which the SAV1 gene was deleted only in the liver, developed hepatocellular carcinoma (HCC), suggesting that deletion of the SAV1 gene is responsible for the development of such carcinomas." (PMID 22185343, 2011). "Several reports have shown that PDK1 can form complex with the Hippo components including MST1/2, SAV1, LATS1/2, and PDK1 recruited to the plasma membrane triggered by PI3K leads to dissociation of these complex and YAP activation in MCF-10A, HEK293T, and hepatocellular carcinoma cells." (PMID 34725466, 2021). "Mouse livers missing Mst1 and Mst2, or SAV1, have elevated YAP activity leading to hepatomegaly and hepatocellular carcinoma (HCC)." (PMID 25097728, 2014).
pancreatic cancer (10 papers, 2015 to 2025). "SAV1 downregulation induces tumorigenesis and metastasis and is closely associated with a poor prognosis of lung and pancreatic cancer." (PMID 37033161, 2023). "SAV1 expression was reported to be decreased in different types of cancer, including colon, lung, renal cell, liver, and pancreatic cancer." (PMID 37033161, 2023). "In pancreatic cancer, miR-181-c is significantly upregulated, correlates with a worse prognosis, and represses the Hippo pathway by directly repressing LATS2, MOB1, MST1, and SAV1, promoting pancreatic cancer cell survival and chemoresistance." (PMID 34575852, 2021). "In the current study, we demonstrated that SAV1 suppressed expression resulted in a promotion of pancreatic cancer development and its suppression was due to promoter hypermethylation." (PMID 28968962, 2017). "In conclusion, this study identified for the first time the suppressor role of SAV1 in pancreatic cancer development and progression." (PMID 28968962, 2017). "In the present study, we aimed to determine SAV1 role and mechanism in pancreatic cancer development and progression." (PMID 28968962, 2017). "Since the role of SAV1 in pancreatic cancer is still unclear, to further understand its role we silenced or overexpressed SAV1 and analyzed the effect in pancreatic cancer cells." (PMID 28968962, 2017). "Our results, together with these evidences suggested that decreased expression of SAV1 in pancreatic cancer was due to promoter hypermethylation." (PMID 28968962, 2017). "Our results showed that SAV1 suppressed expression in pancreatic cancer was due to hypermethylation." (PMID 28968962, 2017). "We then further investigated the relationship between SAV1 expression and pancreatic tumor clinicopathological parameters." (PMID 28968962, 2017). "Although its role in some tumors is known, SAV1 function in other types of tumors, including pancreatic tumor, is still obscure." (PMID 28968962, 2017). "Herein, we reported that miR-181c directly repressed MST1, LATS2, MOB1 and SAV1 expression in human pancreatic cancer cells." (PMID 26561204, 2015). "It was reported that SAV1 repressed the growth of colorectal and pancreatic cancer." (PMID 37033161, 2023). "We then analyze the effect of SAV1 on pancreatic cancer growth and metastasis." (PMID 28968962, 2017). "SAV1 on pancreatic cancer metastasis and apoptosis were also assessed." (PMID 28968962, 2017). "Thus, further studies focusing on the role of SAV1 in the development and progression of some different types of tumors, including pancreatic tumor, are still needed." (PMID 28968962, 2017). "Thus, SAV1 worked as a cancer suppressor and it might be considered as a target for pancreatic cancer therapy." (PMID 28968962, 2017). "Furthermore, SAV1 decreased pancreatic cancer cells invasion and migration, and could promoted pancreatic cancer cells apoptosis, providing new insights into its role in this type of tumor." (PMID 28968962, 2017). "MSI2 modulates pancreatic cancer development through directly binding to the mRNAs of SAV1 and MOB1, thereby controlling the translation and stability of SAV1, as well as the translation of MOB1." (PMID 39890775, 2025). "The cytoplasmic immunolocalization of SAV1 and MOB1A is also in line with previous reports in pancreatic carcinoma for SAV1 and in NSCLC for MOB1A." (PMID 40649713, 2025). "Our results revealed that SAV1 suppressed expression promoted PDAC invasion and migration, and repressed pancreatic cancer cells apoptosis." (PMID 28968962, 2017). "Herein, we demonstrated that miR-181c was substantially overexpressed in pancreatic cancer and induced hyper-activation of YAP/TAZ via directly targeting MST1, LATS2, SAV1 and MOB1." (PMID 26561204, 2015). "miR-181c directly repressed MST1, LATS2, MOB1 and SAV1, leading to YAP/TAZ activation and subsequent promotion of pancreatic cancer cell survival and chemoresistance in vitro and in vivo." (PMID 26561204, 2015).
pancreatic cancer (continued). "In summary, our study has revealed that miR-181c upregulation plays an important role in pancreatic cancer progression and miR-181c is a critical repressor of Hippo signaling by targeting the core kinase cassette, i.e., MST1, LATS2, SAV1 and MOB1." (PMID 26561204, 2015). "A study on pancreatic cancer showed that KDM2B bound to TSS, decreased the levels of H3K27me3, and regulated the expression of a series of genes, and ChIP-sequencing results showed that SAV1 is one of the potential target genes of KDM2B." (PMID 37033161, 2023). "Our results showed a strong SAV1 staining localized predominantly in the cytoplasm of most of the adjacent normal tissue, whereas SAV1 was not expressed in pancreatic cancer tissues." (PMID 28968962, 2017). "However, the effects of SAV1 promoter hypermethylation on pancreatic cancer have not been demonstrated." (PMID 28968962, 2017). "However, SAV1 expression mechanism and effect have not been fully evaluated in pancreatic cancer." (PMID 28968962, 2017). "While YAP signaling clearly supported the proliferation of RNF43-mutant pancreatic cancer, the sgRNAs targeting YAP suppressors SAV1 or LATS1 were not further enriched by ETC-159 treatment, suggesting that YAP activation could not bypass Wnt dependency in RNF43-mutant pancreatic cancer." (PMID 35536676, 2022). "However, these factors are not related to the Wnt-independency phenotype in RNF43-mutant pancreatic cancer, since sgRNAs targeting KDM6A or negative regulators of GLI2 or YAP1, i.e., PTCH1, LATS1, and SAV1, were not enriched in ETC-159 versus vehicle-treated tumors in our initial CRISPR screens." (PMID 35536676, 2022).
lung carcinoma (6 papers, 2016 to 2023). "In this study, we explored exogenous agents that increase SAV1 levels in cancer cells and found that lycorine can correct SAV1 deficiency in lung cancer." (PMID 32439835, 2020). "This work indicates that correcting SAV1 deficiency in lung cancer cells is a new strategy for cancer therapy." (PMID 32439835, 2020). "SAV1 acts as a tumor suppressor in different types of cancer, including pancreatic, colon, and lung cancer." (PMID 37033161, 2023). "Using the Human lung Methylation450K BeadChips data to assess SAV1 promotor methylation level 34, the SAV1 promoter was hypermethylated in lung cancer tissues compared to normal tissues." (PMID 35864957, 2022). "Given that AZA and VP are FDA-approved drugs, this provides a potential and feasible clinical medication regimen for lung cancer patients with low expression of SAV1, particularly the smoking population." (PMID 35864957, 2022). "This work discovered a novel negative YAP-SAV1 feedback loop in normal lung cells, that was dysregulated in lung cancer cells by smoking-related hypermethylated SAV1 promoter." (PMID 35864957, 2022). "Transwell assay and scratch wound assay revealed that exogenous SAV1 in lung cancer cells restrained the invasive ability and migration." (PMID 35864957, 2022). "Using immunodeficient nude mice, the tumorigenic role of SAV1 in lung cancer cells was assessed in vivo." (PMID 35864957, 2022). "We found that overexpression of SAV1 in lung cancer cells activated the Hippo signaling, thus YAP was excluded from the nucleus by phosphorylation." (PMID 35864957, 2022). "Then, we found YAP nuclear exclusion and cytoplasmic retention in SAV1 overexpressing lung cancer cell line compared to the control group." (PMID 35864957, 2022). "Further, bisulfite sequencing PCR (BSP) was used to analyze normal lung and lung cancer tissues where additional methylated CpG islands of SAV1 promoter were determined in cancer." (PMID 35864957, 2022). "Further, YAP activities in lung cancer cells were restrained by SAV1 taking use of YAP/TAZ-responsive TEAD reporter (8xGTIIC-luciferase reporter) and qPCR to measure the expression of YAP target genes." (PMID 35864957, 2022). "This suggested that the methylation of the SAV1 promoter region in lung cancer cells inhibited transcriptional regulation of YAP." (PMID 35864957, 2022). "To further analyze the function of SAV1 in lung cancer, we exogenously expressed SAV1 in lung cancer cell lines and found that exogenous SAV1 repressed the proliferative ability of lung cancer cells in vitro." (PMID 35864957, 2022). "For this study, we used lung cancer cell lines as a model to explore traditional Chinese medicinal herbs that can raise SAV1 expression levels in cancer cells." (PMID 32439835, 2020). "Together, these data indicate that lycorine treatment suppresses tumorigenicity, angiogenesis, invasion, and metastasis of lung cancer cells primarily by increasing SAV1 levels." (PMID 32439835, 2020). "In lung cancer, SAV1 could bind to zinc finger protein Gli1 and negatively regulate the Hedgehog signaling pathway." (PMID 37033161, 2023). "It appeared that SAV1 stabilized MST1 in both lung cancer cell lines, H2170 and HCC827." (PMID 35864957, 2022). "As such, we acknowledged that the malignancy of lung cancer can be reduced by overexpressing SAV1." (PMID 35864957, 2022). "Thus, the expression putative surface markers (CD44, CD133) of stem cells were analyzed in lung cancer cell lines using flow cytometry, where we found that the expression of them was reduced in the overexpressed SAV1 cells compared to the control." (PMID 35864957, 2022). "Functional gene enrichment analysis of RNA transcriptome data of lung cancer cells reflected that except for activating the Hippo signaling pathway, SAV1 exogenous overexpression also influenced the WNT signaling pathway and downregulated the major components of WNT signaling." (PMID 35864957, 2022).
lung carcinoma (continued). "In addition, targeted SAV1 gene therapy combined with TKIs therapies to benefit more smokers with lung cancer is a topic worthy of further study." (PMID 35864957, 2022). "Therefore, SAV1 reduced stem cell-like characteristics of lung cancer cells by suppressing nuclear β-catenin accumulation thus inhibiting WNT signaling pathway." (PMID 35864957, 2022). "Here we found that the small molecule lycorine notably increased SAV1 levels in lung cancer cells by inhibiting SAV1 degradation via a ubiquitin–lysosome system, and inducing phosphorylation and activation of the SAV1-interacting protein mammalian Ste20-like 1 (MST1)." (PMID 32439835, 2020). "The mechanisms of the effect of lycorine on SAV1 protein levels in lung cancer cells is unclear." (PMID 32439835, 2020). "Therefore, we evaluated whether SAV1 promoter methylation influenced transcriptional regulation of YAP in lung cancer cells." (PMID 35864957, 2022). "In our study, it was found that the expression of SAV1 in lung cancer tissue of smoking patients was significantly lower than that of non-smoking patients, and the lentivirus-mediated SAV1 gene transfer could inhibit the growth of NSCLC cells and organoids, especially in smoking patients." (PMID 35864957, 2022). "Further, we analyzed the correlation between the expression of SAV1 and YAP1 in normal lung tissues in the GTEx database as well as normal lung tissues and lung cancer tissues in the TCGA database." (PMID 35864957, 2022). "It was found that the expression of SAV1 and YAP1 was highly and positively correlated in normal lung tissues compared to lung cancer tissues." (PMID 35864957, 2022). "Next, we studied the mechanisms of lycorine-induced increases of tumor-suppressive SAV1 and decreases of oncogenic YAP in the Hippo pathway using a lung cancer cell model." (PMID 32439835, 2020). "We observed that lycorine treatment markedly increased levels of SAV1 and activated MST1 in the Hippo pathway, but significantly decreased the level of oncogenic YAP in lung cancer tissues." (PMID 32439835, 2020). "Bisulfite sequencing PCR (BSP) was used to detect the methylation changes in the SAV1 promoter region in smoking lung cancer and non-smoking lung cancer tissues, where much more methylated CpG sites of SAV1 promoter were discovered in smoking cancer patients." (PMID 35864957, 2022). "To elucidate the mechanism of exogenous SAV1 in inhibiting the malignancy of lung cancer cells and considering that SAV1 is a known suppressor of YAP, we first investigated whether SAV1 affects the components of the Hippo pathway." (PMID 35864957, 2022). "To explore why the YAP-SAV1 negative feedback loop was dysregulated in lung cancer cells, firstly, we used clinical lung samples and confirmed lower expression of SAV1 in cancer tissue versus normal tissue." (PMID 35864957, 2022). "Lycorine treatment did not change total MST1 protein levels or SAV1 mRNA levels in these lung cancer cells." (PMID 32439835, 2020). "A less stringent threshold (RSA ≤ −3 and Q3 z-score ≥1) expanded the list to 171 genes, including negative regulators of YAP signaling such as NF2/Merlin and SAV1, further warranting the importance of YAP signaling in mediating EGFR TKI resistance in lung cancer." (PMID 31741433, 2019). "Furthermore, using the lung cancer organoids, we found that lentivirus-mediated SAV1 gene transfer combined with methylation inhibitor and YAP-TEAD inhibitor is a potential feasible clinical medication regimen for the lung cancer patient, especially among the smoking population." (PMID 35864957, 2022). "Western blotting showed that lycorine treatment not only markedly increased SAV1 protein levels but also dramatically increased phosphorylation of its interacting protein MST1, indicating MST1 protein activation, in SPC-A-1 and A549 lung cancer cells in a concentration-dependent manner." (PMID 32439835, 2020).